MELK (maternal embryonic leucine zipper kinase)
Diseases named in the same sentence as MELK in open-access papers (continued):
Sharing a sentence is not in itself a finding about the gene and the disease.
lymphoma (2 papers, 2019 to 2021). A malignant (clonal) proliferation of B- lymphocytes or T- lymphocytes which involves the lymph nodes, bone marrow and/or extranodal sites. "In conclusion, targeting MELK with OTSSP167 induced strong anti-lymphoma activity both in vitro and in vivo." (PMID 31740676, 2019). "The potential clinical relevance of MELK in the aggressive lymphomas DLBCL and MCL was assessed using publicly available GEP datasets." (PMID 31740676, 2019). "Similarly, OTSSP167 significantly improved the survival of mice in which A20 lymphoma cells were transplanted, which suggests that blocking MELK activity in vivo can also inhibit lymphoma progression." (PMID 34550356, 2021). "In this study, MELK is identified as a novel target in the aggressive lymphomas DLBCL and MCL." (PMID 31740676, 2019). "Consistent with this hypothesis, combining OTSSP167 with venetoclax significantly and highly synergistically enhances the anti-lymphoma effects of the MELK inhibitor in all cell lines tested, even in the highly venetoclax-sensitive ABC-DLBCL cell line U2932." (PMID 31740676, 2019). "First, the effect of the MELK inhibition on lymphoma cell viability was assessed." (PMID 31740676, 2019). "Targeting MELK, using the small molecule OTSSP167, impaired cell growth and survival and induced caspase-mediated apoptosis in the lymphoma cells." (PMID 31740676, 2019).
oral cancer (2 papers, 2023 to 2025). "Gene expression heatmap showed that CEP55 and MELK were highly expressed in oral cancer samples." (PMID 37589542, 2023).
psoriasis (2 papers, 2024). An autoimmune condition characterized by red, well-delineated plaques with silvery scales that are usually on the extensor surfaces and scalp. "TOP2A and MELK genes are highly expressed in psoriasis, and higher expression of TOP2A and MELK is associated with a worse prognosis." (PMID 38382096, 2024). "The main findings of this study indicate that the TOP2A and MELK genes are highly expressed in psoriasis, and higher expression of TOP2A and MELK is associated with a worse prognosis." (PMID 38382096, 2024). "We found that TOP2A and MELK were associated with skin neoplasms, skin diseases, psoriasis, erythema, dermatitis, and infections." (PMID 38382096, 2024). "The expression levels of TOP2A and MELK genes are associated with psoriasis." (PMID 38382096, 2024). "It will involve enrichment analysis and pathway analysis to understand the significant roles of the TOP2A and MELK genes in psoriasis using publicly available datasets." (PMID 38382096, 2024). "We found that core genes (TOP2A, MELK) were highly expressed in psoriasis samples and lowly expressed in normal tissue samples, while DEPDC1B, CCNA2, DLGAP5, NUF2, ASPM were lowly expressed in psoriasis samples." (PMID 38382096, 2024). "CTD analysis found that TOP2A and MELK were related to skin neoplasms, skin diseases, psoriasis, erythema, dermatitis, and infections." (PMID 38382096, 2024). "This study holds potential clinical significance, as the expression levels of TOP2A and MELK may serve as potential biomarkers for assessing the condition and prognosis of psoriasis." (PMID 38382096, 2024). "Core genes (TOP2A, MELK) may play a regulatory role in psoriasis." (PMID 38382096, 2024). "Therefore, it is speculated that the MELK gene may play an important role in the development of psoriasis." (PMID 38382096, 2024). "However, the relationship between the TOP2A and MELK genes and psoriasis is currently unclear." (PMID 38382096, 2024). "However, the influence of the TOP2A and MELK genes on psoriasis remains unclear." (PMID 38382096, 2024). "The gene expression heatmap showed high expression of core genes (TOP2A, MELK) in psoriasis samples, while DEPDC1B, CCNA2, DLGAP5, NUF2, ASPM were lowly expressed in psoriasis samples." (PMID 38382096, 2024).
skin cancer (2 papers, 2022 to 2024). "We found that in skin cancer, both MELK and SH3BP4 were significantly overexpressed in primary tumor compared to adjacent normal, suggesting its role in tumor initiation." (PMID 36741706, 2022).
bladder tumours (1 paper, 2020). "To further confirm the correlations between MELK expression and bladder tumour progression, we tracked two newly diagnosed BCa patients whose tumours occurred within one year." (PMID 31821699, 2020). "The IHC staining results showed that MELK expression in the radical cystectomy BCa tissues was significantly up‐regulated compared with that in the paired paracancerous tissues and the transurethral resection bladder tumour tissues." (PMID 31821699, 2020). "As a cohort study, the tissues were collected from transurethral resection bladder tumour (newly diagnosed tumour) and radical cystectomy (progression tumour) and then performed immunohistochemistry staining to detect MELK expression in progressing bladder tumours." (PMID 31821699, 2020).
gastric tumor (1 paper, 2014). "Here, we showed that MELK expression was up-regulated in gastric tumors." (PMID 24885567, 2014).
high-grade glioma (1 paper, 2024). "Notably, evidence shows that significant elevation of MELK is exhibited in high-grade glioma (HGG) tumors following the failure of radiation and plays a crucial role in tumor radioresistance." (PMID 38970074, 2024).
HIV-1 infection (1 paper, 2017). The type species of lentivirus and the etiologic agent of acquired immunodeficiency syndrome (AIDS). "The main finding of the present study is that MELK regulates CA disassembly to promote viral cDNA synthesis through the phosphorylation of Ser-149 in CA during the early stages of HIV-1 infection." (PMID 28683086, 2017). "In conclusion, the essential role of MELK at an early stage of HIV-1 infection exemplifies another aspect of the functional links between viral capsid disassembly, cDNA synthesis and nuclear import." (PMID 28683086, 2017). "The marked suppression of the spread of HIV-1 infection in MELK-depleted cells further suggests a role for MELK in other stages of virus replication." (PMID 28683086, 2017). "Overall, these results suggest that phosphorylation of Ser-149 by MELK is a trigger for CA disassembly in HIV-1 infection." (PMID 28683086, 2017). "The results suggest that MELK is required for HIV-1 infection during a post-entry stage." (PMID 28683086, 2017). "We next examined whether forced expression of MELK in MT4C5 cells affects HIV-1 infection." (PMID 28683086, 2017). "To determine whether endogenous MELK is involved in HIV-1 infection, we depleted this enzyme from MT4C5 cells (MELK-KD)." (PMID 28683086, 2017). "Although MELK was identified based on HIV-1 infection-resistant cells during a spreading-infection, the inhibition by MELK-depletion in single-round infection assays was not complete." (PMID 28683086, 2017). "MELK depletion did not significantly alter the efficiency of HIV-1 entry, but did impair viral cDNA synthesis in association with a significant delay of CA disassembly during the early stages of HIV-1 infection." (PMID 28683086, 2017). "Overexpression of MELK but not the MELK mutant inhibited HIV-1 infection (compare CSII-control, CSII-MELK and CSII-MELK T167A) and resulted in aberrant viral cDNA synthesis quite similar to the S149E CA mutant (compare CSII-Control, CSII-MELK and CSII-MELK-T167A)." (PMID 28683086, 2017).
Hyperinsulinemia (1 paper, 2024). An increased concentration of insulin in the blood. "Additionally, hyperinsulinemia inhibited the transcriptome required for cell cohesion MELK, CDCA7, ESCO2, mitotic spindle assembly KIF15, SGO1, and AURKB, and kinetochore formation KNL and NDC80." (PMID 39768214, 2024).
influenza (1 paper, 2025). An acute viral infection of the respiratory tract, occurring in isolated cases, in epidemics, or in pandemics; it is caused by serologically different strains of viruses (influenzaviruses) designated A, B, and C, has a 3-day incubation period, and usually lasts for 3 to 10 days. "To further validate the anti-influenza potential of targeting MELK, we employed another pharmacological inhibitor, MELK-8a." (PMID 40539108, 2025). "OTS167, a pharmacological inhibitor of MELK currently undergoing phase II clinical trials for treating cancer, potently inhibits influenza virus infections in vitro and in mice, representing a promising lead for developing novel influenza antivirals." (PMID 40539108, 2025).
intrahepatic cholangiocarcinoma (1 paper, 2019). A carcinoma that arises from the intrahepatic bile duct epithelium in any site of the intrahepatic biliary tree. "In the present study, we sought to determine the function of MELK in human intrahepatic cholangiocarcinoma (iCCA) by evaluating the levels of MELK and some of its targets in a collection of human iCCA and corresponding non-tumorous surrounding livers." (PMID 31861475, 2019).
meningioma (1 paper, 2023). A generally slow growing tumor attached to the dura mater. "Furthermore, of the four DREAM complex target genes shown to be upregulated in type C tumors, only PBK was higher in our NF2-2 meningiomas, while the expression of the 3 other genes (TTK, MELK, and CDK1) was not significantly different between the subgroups." (PMID 36937440, 2023).
metastatic melanoma (1 paper, 2021). A melanoma that has spread from its primary site to another anatomic site. "Indeed, we observed that MELK, as well as CDK1, is significantly overexpressed in metastatic melanoma." (PMID 33431809, 2021).
pancreatic adenocarcinoma (1 paper, 2019). "This study analysis also exhibited similar results, and MELK was linked with poor survival in pancreatic adenocarcinoma." (PMID 31412643, 2019). "DNA topoisomerase II alpha, syndecan 1, maternal embryonic leucine zipper kinase and proto-oncogene receptor tyrosine kinase Met were significantly linked with poor survival in pancreatic adenocarcinoma." (PMID 31412643, 2019). "The survival analysis results showed that MELK and TOP2A were linked with poor survival in pancreatic adenocarcinoma (p < 0.01)." (PMID 31412643, 2019).
pancreatic ductal adenocarcinoma (1 paper, 2014). An infiltrating adenocarcinoma that arises from the epithelial cells of the pancreas. "To study whether MELK plays a role in cellular migration, we used the human pancreatic ductal adenocarcinoma cell line Panc‐1 as a model." (PMID 25194022, 2014).
prostate tumour (1 paper, 2018). "We found that MELK is overexpressed in human prostate tumours on the protein level, consistent with a previous study." (PMID 29437778, 2018). "As MELK is most highly expressed in aggressive prostate tumours, we chose the metastatic, castration‐resistant C4‐2b cell line as our main model system." (PMID 29437778, 2018). "After first validating the overexpression of MELK mRNA in a second, independent set of PB‐Cre/PtenloxP/loxP and the PB‐Cre/p53loxP/loxPRbloxP/loxP prostate tumour samples (Fig EV3A), we aimed to confirm that MELK expression is also increased at the protein level in these tumours." (PMID 29437778, 2018).
pulmonary hypertension (1 paper, 2025). Increased pressure within the pulmonary circulation due to lung or heart disorder. "To investigate the role of MELK inhibition in pulmonary hypertension, we employed a Sugen/hypoxia (Su/H) mouse model and treated mice with the MELK inhibitor OTS167 (5 mg/kg, IP daily) or saline starting at the end of week 1 for 3 weeks." (PMID 41278210, 2025). "OTS167 treatment attenuated pulmonary hypertension, right ventricular hypertrophy, and pulmonary vascular remodeling in Su/H mice, supporting the therapeutic potential of targeting MELK signaling in PAH." (PMID 41278210, 2025). "Collectively, these results demonstrate that pharmacological inhibition of MELK by OTS167 effectively attenuates pulmonary hypertension, RV hypertrophy, and pulmonary vascular remodeling in Su/H mice." (PMID 41278210, 2025).
retinoblastoma (1 paper, 2022). A malignant tumor that originates in the nuclear layer of the retina. "Treatment of Y-79 human retinoblastoma cell line with CA was able to inhibit the expression levels of MELK and FoxM1 while also reducing the transcriptional activity of FoxM1 to a baseline level." (PMID 36012159, 2022).
teratocarcinoma (1 paper, 2015). A germ cell tumor characterized by the presence of an embryonal carcinoma component and a teratoma component. "Shortly after the discovery of MELK in mouse egg and preimplanation embryos, a second group cloned MELK—also known as MPK38 (Murine protein serine/threonine kinase 38)—from a murine teratocarcinoma cell line, PCC4." (PMID 25852826, 2015).
Uterine leiomyoma (1 paper, 2020). The presence of a leiomyoma of the uterus. "According to the data obtained from GEO regarding 15 ULMS samples, seven uterine leiomyoma (ULM), and four myometrium (MM), we detected that MELK expression was significantly overexpressed in ULMS compared to those in ULM and in MM (P < 0.01)." (PMID 32391256, 2020).
viral infection (1 paper, 2026). "Intriguingly, super-resolution imaging reveals that MELK colocalizes with the cellular actin cytoskeleton that is required for viral infection." (PMID 42091603, 2026).
cancer (140 papers, 2006 to 2026). A tumor composed of atypical neoplastic, often pleomorphic cells that invade other tissues. "MELK, a serine/threonine kinase implicated in cancer stem cell maintenance and chemoresistance in multiple malignancies, was associated with poor prognosis." (PMID 40709174, 2025). "MELK is a serine/threonine kinase that is overexpressed in several cancer types and is associated with poor prognosis and aggressive tumor behavior." (PMID 40076867, 2025). "Given MELK’s reported association with metastasis in various cancers, we investigated its role in invasion using the Fluoroblok Tumor Invasion Assay, modified to measure absorbance from stained cells." (PMID 40076867, 2025). "The expression of 74 genes can influence the activity of multiple cancer hallmark-related pathways, such as MELK, CDC25C, and AURKA." (PMID 39940833, 2025). "The role of MELK in cancer has been of increasing interest because of its elevated expression in various cancer tissues and its association with poor patient outcomes." (PMID 37377604, 2023). "MELK is overexpressed in various cancers, and high MELK expression is associated with infaust prognosis and has been identified as a prospective target for multiple cancer types." (PMID 37008632, 2023). "MELK expression level correlates with malignancy grade, and MELK is a marker of cancer stem cells and is generally associated with poor prognosis." (PMID 37175795, 2023). "It has been reported that MELK is significantly upregulated in multiple types of human cancer and associated with poor prognosis." (PMID 37949877, 2023). "And the genes regulated by BBOX1-AS1 are also associated with other cancer-related signaling pathways, including the Wnt/β-catenin signaling pathway and MELK/FAK signaling." (PMID 37925403, 2023). "In conclusion, we demonstrated elevated expression of MELK in various human cancers, including HCC, which was linked to poor survival outcomes." (PMID 35511171, 2022). "MELK was shown to have roles in many cancer-associated processes including tumor growth, chemotherapy resistance, and tumor recurrence." (PMID 34550356, 2021). "MELK overexpression is associated with poor prognosis in cancer as it promotes cancer cell survival and has strong implications for regulating cell cycles by causing G2/M arrest." (PMID 34575883, 2021). "MELK (Maternal embryonic leucine-zipper kinase)/FoxM1(Forkhead box M1) signaling is estimated to be up-regulated in various cancers and associated with tumor growth, metastasis, angiogenesis and chemoresistance." (PMID 32581798, 2020). "Several studies observed high MELK levels in different types of cancer and MELK overexpression is often associated with a poor prognosis." (PMID 31740676, 2019). "Maternal embryonic leucine zipper kinase (MELK) plays a role in cancer cell cycle progression and is associated with poor prognosis in several cancer cell types." (PMID 31740676, 2019). "In recent study utilizing various MELK knockouts across several cancer types, authors demonstrated that MELK deficiency didn't alter tumor growth." (PMID 31380279, 2019). "Although MELK has been implicated in each of these processes, our results demonstrate that MELK-knockout cancer cell lines grow at wild-type levels in a variety of assays designed to test these pathways." (PMID 29417930, 2018). "MELK is over-expressed in these cancers, and high expression of MELK is associated with poor patient prognosis." (PMID 29417930, 2018). "MELK over-expression is associated with aggressive disease, and MELK has been implicated in numerous cancer-related processes, including chemotherapy resistance, stem cell renewal, and tumor growth." (PMID 29417930, 2018). "A number of the authors on the first of these articles were also authors on the 2014 eLife article that implicated MELK as a therapeutic target in human cancer." (PMID 29417929, 2018).